LCAT (lecithin-cholesterol acyltransferase)
Diseases named in the same sentence as LCAT in open-access papers (continued):
Sharing a sentence is not in itself a finding about the gene and the disease.
atherosclerosis (continued). "Furthermore, the present study demonstrated a significant positive correlation between plasma LCAT and PON-1, suggesting that the two lipoprotein-associated enzymes may play synergistic roles on HDL particles to counter the effects of atherosclerosis and ASCVD progression." (PMID 39114750, 2024). "Therefore, the exact role of LCAT in the pathogenesis of atherosclerosis is still not fully known." (PMID 23479335, 2013). "Existing data in humans are controversial, but markedly support the idea that decreased LCAT concentration and activity, despite reducing HDL levels, are not related with the pathogenesis of atherosclerosis." (PMID 33807918, 2021).
Fish-eye disease (38 papers, 2007 to 2025). Fish eye disease (FED) is a form of genetic LCAT (lecithin-cholesterol acyltransferase) deficiency (see this term) characterized clinically by corneal opacifications, and biochemically by significantly reduced HDL cholesterol and partial LCAT enzyme deficiency. "LCAT deficiency, also known as Fish Eye Disease (FED), is a rare recessive genetic disorder with only a few cases reported worldwide." (PMID 40476138, 2025). "Fish-eye disease (FED) and familial lecithin-cholesterol acyltransferase (LCAT) deficiency (FLD) are rare." (PMID 41542003, 2025). "Seven cases (14%) had familial LCAT deficiency or fish-eye disease, which also has low LCAT activity from genetic mutations." (PMID 38338310, 2024). "Familial lecithin:cholesterol acyltransferase (LCAT) deficiency (FLD) is a rare genetic disease caused by the loss of function mutations in the LCAT gene." (PMID 37627492, 2023). "We have identified one IC with a compound heterozygosity in LCAT causing Fish Eye Disease and one IC with a variant in ABCA1 in homozygosity causing Tangier disease." (PMID 37138899, 2022). "Over 90 genetic mutations in LCAT have been described that lead to one of two characterized diseases: fish eye disease and familial LCAT deficiency." (PMID 36588724, 2022). "Syndromes associated with LCAT deficiency, a rare autosomal recessive condition, include fish-eye disease (FED) and familial LCAT deficiency (FLD)." (PMID 35065092, 2022). "Familial lecithin:cholesterol acyltransferase (LCAT) deficiency (FLD, OMIM#245900) is a rare recessive disorder of HDL metabolism, due to loss‐of‐function mutations in the LCAT gene." (PMID 34761839, 2022). "Fish eye disease, also called partial lecithin cholesterol acyltransferase (LCAT) deficiency is caused by mutations in the LCAT gene." (PMID 34250435, 2021). "There was a significantly greater risk of premature coronary artery disease in fish eye disease compared to familial LCAT deficiency." (PMID 34256778, 2021). "This peculiar profile is clearly related to the residual amount of circulating LCAT, as shown by the gene-dose dependent effect observed for these biomarkers in carriers of genetic LCAT deficiency." (PMID 32708515, 2020). "We also report here cholesterol and phospholipid accumulation in a cornea from a patient with ABCA1 deficiency and LCAT deficiency (Fish-eye disease)." (PMID 31779197, 2019). "Genetic, biochemical, in vitro and in silico analyses indicate that the rare mutations p.M404 V and p.V333 M in LCAT gene lead to suppression of LCAT enzyme activity and cause clinical features of familial LCAT deficiency." (PMID 31164121, 2019). "Mutations in LCAT gene causes familial LCAT deficiency, which is characterized by very low plasma HDL-cholesterol levels (Hypoalphalipoproteinemia), corneal opacity and anemia, among other lipid-related traits." (PMID 31164121, 2019). "Our aim is to evaluate clinical/biochemical features of a Chilean family with a proband showing clinical signs of familial LCAT deficiency, as well as to identify and assess the functional effects of LCAT mutations." (PMID 31164121, 2019). "Two different syndromes with different biochemical and clinical features are caused by mutations in the LCAT gene, namely Familial LCAT deficiency (FLD) and Fish-Eye disease (FED)." (PMID 26919698, 2016). "Patients suffering from classical LCAT deficiency or from other genetic errors disrupting the HDL reverse transport pathway (such as Tangier's disease or Fish Eye Disease) suffer from opacities of the central cornea." (PMID 18331643, 2008). "It is noteworthy that corneal lipid deposition is observed in three other human genetic disorders of cholesterol, specifically high density lipoprotein (HDL), metabolism: Niemann-Pick type C, LCAT deficiency (fish-eye disease) and ABCA1/Tangier Disease (TD)." (PMID 17668063, 2007).
Fish-eye disease (continued). "Genetic syndromes such as Schimke immuno-osseous dysplasia, familial lecithin-cholesterol acyltransferase deficiency with two clinical variants (fish-eye Disease and the p.Leu364Pro mutation), lead to NS through mechanisms involving podocyte and lipid metabolism dysfunction." (PMID 40868160, 2025). "Therefore, a plenty of studies and clinical investigations were aimed at promoting plasma lipid metabolism by enhancing the activity of LCAT to find better managements choices for familial LCAT deficiency (FLD) and cardiovascular disease." (PMID 40927188, 2025). "Renal disease represents the major cause of morbidity and mortality in familial LCAT deficiency cases, but it is unknown whether the levels of LCAT in HDL associate with the development of CVD in CKD patients." (PMID 34634315, 2021). "Interestingly, familial lecithin-cholesterol acyltransferase (LCAT) deficiency and fish eye disease caused by partial loss-of-function of LCAT also exhibit evident corneal opacification due to free cholesterol accumulation." (PMID 31323021, 2019). "In addition to its importance in RCT, mutations in the LCAT gene result in metabolic disorders, such as familial LCAT deficiency and fish-eye disease in which the body’s ability to metabolize CHOL is severed, leading to corneal lipid deposition, hemolytic anemia, and finally renal failure." (PMID 29438987, 2018). "LCAT abnormalities result in two rare autosomal recessive disorders: familial LCAT deficiency (FLD) and fish-eye disease (FED)." (PMID 41542003, 2025). "Mutations in the LCAT protein, which causes a loss, or reduction, of LCAT activity, are responsible for familial LCAT deficiency (FLD), or fish eye disease (FED)." (PMID 38455763, 2024). "It is noteworthy that systemic dyslipoproteinemias, including fish-eye disease (FED), Tangier disease (TD), and familial lecithin–cholesterol acyltransferase (LCAT) deficiency (FLD) may also lead to corneal lipid deposition." (PMID 37175019, 2023). "LCAT gene mutation is responsible for somatic diseases, such as familial LCAT deficiency (FLD) and fish-eye disease (FED) 10, due to complete loss of LCAT activity, resulting from the matrix loss due to HDL particles by LCAT activity." (PMID 36903601, 2023). "Genetic LCAT deficiency is associated with the development of two syndromes: (i) familial LCAT deficiency (FLD) and (ii) fish-eye disease (FED)." (PMID 36651718, 2023). "Familial lecithin:cholesterol acyltransferase (LCAT) deficiency (FLD) is a rare and recessive genetic disease caused by mutations in the LCAT gene." (PMID 37627492, 2023). "Compound homozygous or heterozygous mutations in the LCAT gene cause LCAT enzyme deficiency, and two entities are described: Norum disease (OMIM 245,900) and fish-eye disease (FED/Partial LCAT deficiency) (OMIM 136,120)." (PMID 35743896, 2022). "LCAT (lecithin-cholesterol acyltransferase) deficiency is characterized by two distinct phenotypes, familial LCAT deficiency (FLD) and Fish Eye disease (FED)." (PMID 34256778, 2021). "Familial LCAT deficiency (FLD, OMIM# 245900) is a rare autosomal recessive condition caused by loss-of-function mutations in the gene encoding LCAT." (PMID 33807271, 2021). "LCAT enzyme deficiency, caused by homozygous or compound heterozygous mutations in the LCAT gene, causes the appearance of two autosomal recessive diseases: Norum disease (OMIM 245900) and fish-eye disease (FED/Partial LCAT deficiency) (OMIM 136120)." (PMID 37510094, 2023). "Hypoalphalipoproteinemia includes the following diseases: Tangier disease, Apolipoprotein A-I (APOA1) deficiency, and Lecithin cholesterol acyltransferase (LCAT) deficiency (including Familial LCAT deficiency (FLD) and Fish eye disease (FED)) (Hegele 2020 review)." (PMID 37138899, 2022). "This is not surprising, since genetically reduced LCAT levels and activity, as in familial LCAT deficiency, lead to severe HDL defects and, importantly, to renal dysfunction." (PMID 33807271, 2021).
Fish-eye disease (continued). "Mutations in both alleles of LCAT gene may lead to two syndromes, namely familial LCAT deficiency (FLD) and fish eye disease (FED)." (PMID 31684177, 2019). "Mutations in the LCAT gene (gene ID = 3931) have been related to the severe LCAT deficiency, known as Familial LCAT deficiency (FLD) (OMIM#245900) and to the partial LCAT deficiency, referred to as Fish eye disease (OMIM#136120)." (PMID 31164121, 2019). "It seems unlikely that the proposed detrimental effects of LP-Z could be explained by compromised LCAT activity alone because liver insufficiency is not a feature of genetic LCAT deficiency." (PMID 35268313, 2022). "However, comparing NMR data from LCAT deficiency patients and subjects with low HDL cholesterol levels, there were differences in some lipoprotein variables, which identified a distinctive lipoprotein profile in patients with LCAT deficiency." (PMID 31684177, 2019). "There are two clinical variants of LCAT deficiency: (A) fish-eye disease (FED)—the disease occurs due to the partial absence of LCAT enzyme activity, and (B) the familial form of LCAT deficiency—the disease occurs due to the complete absence of LCAT enzyme activity." (PMID 40868160, 2025). "The normal functioning of LCAT is reduced or completely lacking in individuals suffering from the autosomal recessive disorders familial LCAT deficiency (FLD) and fish-eye disease (FED)." (PMID 33720934, 2021).
Obesity (29 papers, 2013 to 2025). Accumulation of substantial excess body fat. "Studies have shown that LCAT deficiency provides specific protection against diet-induced obesity and insulin resistance by regulating white adipose tissue formation and brown fat cell allocation." (PMID 38918701, 2024). "The obesity-related reduction of lyso-phospholipids has been associated with impaired lecithin cholesterol acyltransferase activity." (PMID 39261864, 2024). "Studies suggest the inverse association of LPC with obesity may be related to the transfer of PC to cholesterol by lecithin-cholesterol acyltransferase (LCAT) or LPC catabolism, resulting in lower levels of LPC present in the blood." (PMID 39905412, 2025). "The increase in LCAT activity in obesity and obesity-associated low-grade inflammation may represent a compensatory mechanism." (PMID 36902082, 2023). "Since lecithin-cholesterol acyltransferase (LCAT) activity has been reported to be inversely associated with obesity, it is tempting to speculate that increasing CE’s abundance in both cohorts was related to the restoration of normal LCAT functionalities." (PMID 37571279, 2023). "Thus, it appears that the concentration and activity of LCAT increases with obesity and obesity-associated low-grade inflammation, suggesting a compensatory mechanism, but appears to decrease when it comes to severe comorbidities and pathological conditions." (PMID 33673728, 2021). "The LCAT knockout mice are resistant to obesity, hepatic endoplasmic reticulum stress and hepatic endoplasmic reticulum cholesterol." (PMID 37756351, 2023). "In conclusion, our results suggest that central obesity and MetS are associated with an impairment of phospholipid remodelling and HDL composition, partially led by reduced LCAT activity and correlating with obesity and insulin resistance." (PMID 35743227, 2022). "In the present study, we found that obesity was associated with marked changes in CETP and LCAT activities and altered HDL composition, such as decreased apoA-I, cholesterol, and phospholipid levels, while serum amyloid a levels were increased." (PMID 33673728, 2021). "Dr. Ng shared that LCAT-null mice were protected from diet-induced obesity, insulin resistance, and nonalcoholic fatty liver disease." (PMID 32482717, 2020). "We previously reported, in our original article, a patient with obesity who responded to prescribed dietary control with weight reduction accompanied by lowering of the serum levels of TRLs and LCAT activity, and a decrease of the LDL-Rm value." (PMID 30518338, 2018). "In addition, some studies have found that LCAT expression and activity are downregulated in some cases of obesity and metabolic syndrome, possibly due to chronic low-grade inflammation, insulin resistance, and other factors." (PMID 37687178, 2023). "Furthermore, the enzyme LCAT is largely responsible for generating plasma LPLs, and LCAT is present in low-density lipoproteins, which are increased in individuals with obesity, insulin resistance, and fatty liver disorders [reviewed in detail refs 8 and 38]." (PMID 28740130, 2017). "Thus, animals with obesity tend to have significantly more intense lipid peroxidation, lower levels of antioxidants, and reduced activity levels of LCAT and PON." (PMID 23936611, 2013). "Recent studies in LCAT-deficient mouse models suggested that the absence of LCAT could have a protective effect against insulin resistance, diabetes, and obesity." (PMID 37510094, 2023). "Accordingly, it has been shown that SCD1, LPCAT3, and LCAT activity correlates with membrane saturation, wherein elevated ER stress was observed upon loss of either SCD1 or LPCAT3 activity, and was associated with an increased level of LCAT in animal models of either obesity or overnutrition." (PMID 33277471, 2020). "Obesity and insulin resistance induce HDL remodeling through oxidative stress, impairing anti-inflammatory functions by suppressing lecithin-cholesterol acyltransferase activity." (PMID 40483478, 2025).
Obesity (continued). "Several of the observed DMCs were located in genes related to T2D or obesity, such as ALOX12, PAMR1, and GNAS in WB; IRS1, LEP, and ADIPOQ in SAT; LCAT, FOXA2, KCNQ1, and GCKR in VAT; and PKD4, HNF4A, XBP1, and PON1 in LT." (PMID 29466957, 2018). "We also identified six DMRs which mapped to obesity and related metabolic traits in the GWAS catalogue (PROX1, PHACTR1, SLC22A8, SMAD3, LCAT, DNM2)." (PMID 25651499, 2015). "“Enoant” administration restored blood indices in rats with obesity and reduced peroxidation processes and normalized the PON and LCAT activity levels in old rats." (PMID 23936611, 2013). "We observed an obesity-related reduction in LCAT activity in maternal serum as well as a nonsignificant trend in cord blood (p = 0.077)." (PMID 36671061, 2023). "However, recent study showed an increased plasma LCAT activity on average 12% higher in subjects with a fatty liver index (FLI) ≥ 60 as well as in insulin-resistant conditions, like obesity, T2DM, and MetS." (PMID 36588724, 2022). "What’s more, some key enzymes involved in HDL metabolism, such as cholesteryl ester transfer protein (CETP), lecithin/cholesterol acyltransferase (LCAT), hepatic lipase (HL) and protein phospholipid transfer protein(PLTP), are changed in people with obesity who have insulin resistance." (PMID 31842884, 2019). "Although the important effects of LCAT in HDL-C and TG metabolism are known, the role of LCAT in metabolic disorders, including obesity and DM, has not been sufficiently studied." (PMID 37510094, 2023).
LCAT deficiency (28 papers, 2012 to 2025). LCAT (lecithin-cholesterol acyltransferase) deficiency is a rare lipoprotein metabolism disorder characterized clinically by corneal opacities, and sometimes renal failure and hemolytic anemia, and biochemically by severely reduced HDL cholesterol. "Mutations of LCAT gene cause familial LCAT deficiency, a metabolic disorder characterized by hypoalphalipoproteinemia." (PMID 22658148, 2012). "It is now understood that these two disorders represent a continuum of LCAT deficiency with FLD patients having a more profound decrease in total LCAT activity." (PMID 38455763, 2024). "Corneal opacity is often the first clinically recognized sign of LCAT deficiency and was present in all FLD and FED patients at the time of report." (PMID 35065092, 2022). "Pathologically, LCAT deficiency can result in impaired vision, due to cholesterol corneal opacities, as well as anemia and renal damage as occurs in familial lecithin:cholesterol acyltransferase deficiency (FLD) disease, an autosomal recessive disorder." (PMID 38455763, 2024). "In familial LCAT deficiency (FLD) patients, intravenous administration of ACP-501, the recombinant human LCAT, improved the abnormal distribution of HDL subfractions and decreased TG levels after meals." (PMID 38952543, 2024). "LCAT deficiency manifests two distinct phenotypes, FLD and FED." (PMID 37138899, 2022). "Lecithin:cholesterol acyltransferase (LCAT) and LCAT-activating compounds are being investigated as treatments for coronary heart disease (CHD) and familial LCAT deficiency (FLD)." (PMID 30479275, 2018). "In familial LCAT deficiency (FLD) patients, loss of function of LCAT results in lower plasma HDL-C, which may contribute to the pathogenesis of corneal opacity, dyslipidemia and proteinuria with a poor renal prognosis." (PMID 28107429, 2017). "Mutations in the LCAT gene cause two rare disorders, namely familial LCAT deficiency, FLD (MIM n." (PMID 24736652, 2014). "Of the 219 articles that met the inclusion criteria for our review, 207 studies reported information on human patients with primary LCAT deficiency and 12 studies reported information on the biochemical properties of FED-causing and FLD-causing variants." (PMID 35065092, 2022). "Here, we systematically review observational studies of FLD, FED, and heterozygous subjects, which summarize available evidence on the natural history and biomarkers of LCAT deficiency, in order to guide the development of novel therapeutics." (PMID 35065092, 2022).